CD99 (CD99 molecule (Xg blood group))
Diseases named in the same sentence as CD99 in open-access papers (continued):
Sharing a sentence is not in itself a finding about the gene and the disease.
synovial sarcoma (37 papers, 2006 to 2025). "Tumour cells were immunoreactive for transducer-like enhancer of split 1 (TLE1) and cluster of differentiation 99 (CD99) with a score of 4+ and 3+, susceptible and specific for monophasic synovial sarcoma diagnosis." (PMID 38410005, 2024). "The possibility of a monophasic synovial sarcoma of the oropharynx, considering the positivity for cytokeratins, CD99, and BCL2, or of its variant ossificans form, is discarded by the absence of an SYT translocation." (PMID 28050299, 2016). "However, Bcl-2, CD99 and cytokeratin are characteristic markers commonly associated with synovial sarcomas." (PMID 41561516, 2025). "While the cytokeratin expression in small cell synovial sarcoma can be variable, its presence can still be helpful in a synovial sarcoma diagnosis when interpreted in conjunction with other markers like CD99 and TLE1." (PMID 40861426, 2025). "Synovial sarcoma is positive for CD99, TLE1, focally AE1/AE3, and EMA, and has a characteristic SS18-SSX gene fusion." (PMID 37735390, 2023). "Approximately 90% of synovial sarcomas are positive for keratin, and approximately 60% of cases will be positive for CD99." (PMID 35655305, 2022). "The specimens of our patient were uniformly positive for Vimentin, BCL-2 and CD99 (markers which are typical for synovial sarcoma) and showed focal positivity for EMA." (PMID 24715974, 2014). "Bcl-2 protein is regularly expressed in synovial sarcomas, and CD99, the product of the MIC2 gene, is seen in 67% of all cases." (PMID 23762651, 2013). "Unless other areas of biphasic or monophasic synovial sarcoma are seen, and because they usually show membranous CD99 immunoreactivity, immunohistochemical distinction of poorly differentiated synovial sarcoma from EFT may be difficult." (PMID 40950824, 2025). "Most cases of synovial sarcomas also express CD99 (membranous staining) and Bcl-2." (PMID 35565289, 2022). "T lymphoblastic lymphoma, poorly differentiated synovial sarcomas, stromal tumors, and rare rhabdomyosarcoma may show CD99 positivity." (PMID 23537038, 2013). "Positive staining for CD99 and bcl-2 is also present in many cases of synovial sarcoma." (PMID 22741534, 2012). "However, a precise definitive diagnosis of synovial sarcoma was made using ancillary techniques; CD99 and TLE-1 could be detected immunohistochemically to confirm the diagnosis." (PMID 40578241, 2025). "Synovial sarcomas (SSs) reveal diffuse expression of the apoptosis regulator BCL2 and often express a transmembrane glycoprotein CD99 (detected in >60% of the cases)." (PMID 41155410, 2025). "In contrast, synovial sarcoma exhibits a biphasic or monophasic spindle cell morphology with specific markers like TLE1, CD99, and Bcl-2, which aid in differentiation." (PMID 40578241, 2025). "Most synovial sarcomas show an immunoreaction for cytokeratin and epithelial membrane antigen (EMA) The positive rates for S‐100 protein, CD99, and Bcl2 are 30%, 60%–70%, and 75%–100%, respectively." (PMID 40964824, 2025). "Markers that are commonly expressed on synovial sarcoma cells include epithelial membrane antigen (EMA), BCL-2, and vimentin, while markers such as protein S-100, CD99, CD34, actin, and desmin are mostly negative." (PMID 40130143, 2025). "The open biopsy confirmed a spindle mesenchymal tumor with positive immunohistochemistry for CD99 (focal membrane staining), TLE-1 (nuclear staining), and BCL-2 (cytoplasmic staining), consistent with mediastinal synovial sarcoma." (PMID 39015801, 2024). "Immunohistochemical examination and CD99, TLE1, and BCL2 results were positive, so the diagnosis of synovial sarcoma was confirmed." (PMID 39015801, 2024). "Synovial sarcoma expresses Epithelial Membrane Antigen (EMA) and cytokeratins in 90% of cases, CD99 in 60% of cases and S100 protein in 30% of cases." (PMID 34194735, 2021). "Synovial sarcomas are usually positive for vimentin, epithelial membrane antigen (EMA), bcl-2, CD99 (60–90%), and S-100 (30%)." (PMID 26101678, 2015).
synovial sarcoma (continued). "Although CD99 shows strong membrane positivity in EFT, it can also be positive in other tumors like lymphoblastic lymphoma, rhabdomyosarcoma, synovial sarcoma, mesenchymal chondrosarcoma, Wilms tumor and rarely in DSRCT." (PMID 25206203, 2013). "Immunohistochemically, the majority of synovial sarcomas express cytokeratins, epithelial membrane antigen, calponin, B-cell lymphoma 2 (BCL-2) and CD-99." (PMID 23148739, 2012). "Overexpression of the surface membrane protein CD99 is a universal feature of EFTs but not pathognomonic because it is also found in synovial sarcomas and gastrointestinal stromal tumors." (PMID 24523977, 2014). "Synovial sarcoma are also positive for EMA, vimentin, BCL-2, CD99 and calponin." (PMID 16907985, 2006). "Histologically, CCSK can mimic myxoid variant of synovial sarcoma (SS); however, the double positivity for CD99 and TLE1 in SS helps in excluding CCSK." (PMID 30410809, 2018). "It is not clear if CD99 contributes to the oncogenesis of synovial sarcoma." (PMID 29509716, 2018). "In common with other synovial sarcomas, the immunohistochemical staining demonstrated some typical findings of synovial sarcoma: the tumor cells were positive for vimentin and CD99, but negative for CD34, Bcl-2, alpha smooth muscle actin, desmin, and S-100 protein." (PMID 24969223, 2014). "Importantly, CD99 is not specific and may be positive in many other tumors: synovial sarcoma, acute lymphoblastic leukemia, melanoma, solitary fibrous tumor, BCOR-rearranged sarcoma, angiomatoid fibrous histiocytoma, neurothekeoma, and calcifying aponeurotic fibroma." (PMID 35565289, 2022). "In our case, immunohistochemistry confirmed the diagnosis of monophasic synovial sarcoma, with the tumor cells being non-reactive for S-100, Smooth Muscle Actin (SMA), and neurofilament, but positive for TLE1, BCL2, and CD99, which are indicative of this type of sarcoma." (PMID 39364429, 2024). "All synovial sarcomas were negative for CD34 and positive for both bcl2 and CD99." (PMID 24131748, 2013).
sarcoma (31 papers, 2008 to 2026). A usually aggressive malignant neoplasm of the soft tissue or bone. "For diagnostic purposes, we confirm that focal expression of CD99 in a small round cell sarcoma should raise the differential diagnosis of CIC-rearranged sarcoma." (PMID 40722508, 2025). "Furthermore, approximately 50% of myoepitheliomas have translocations involving the EWSR1 gene, such as EWSR1::POU5F1 sarcoma, and myoepithelioma can also exhibit positive expression of CD99 and NKX3.1, posing a significant diagnostic challenge." (PMID 38254207, 2024). "Histopathology revealed a small round cell tumor with strong membranous CD99 expression consistent with an intracranial Ewing-like sarcoma." (PMID 42293494, 2026). "In good accordance with these findings, the primary tumor in the patient localized in his left nasal cavity, showed positivity for both neuroendocrine (synaptophysin, CD56) and sarcoma markers (CD99), and had a high proliferation index." (PMID 40134582, 2025). "Immunohistochemical staining shows that EWSR1/FUS::NFATC2 sarcoma often expresses markers such as CD99, NKX3.1." (PMID 38254207, 2024). "In cell lines, the high level of CD99 at the transcriptional RNA level was observed in sarcoma (i.e., ASC diff, NX-value: 124.2), foreskin fibroblasts (i.e., BJ hTERT, NX-value:100.3), and malignant glioma (i.e., U138 MG, NX-value: 49.6) cells." (PMID 34611477, 2021). "Use of flow cytometry to identify sarcoma CTCs, based on expression of either CD99 or cell surface vimentin, has been reported." (PMID 29108279, 2017). "NFATC2 sarcomas express diffuse CD99 (like ES) in about 50% of cases; NKX2.2, dot-like keratin, and PAX7 positivity may also be observed." (PMID 36941503, 2023). "Experiments using siRNA were performed to investigate whether CD99 and CD73 were associated with the regulation of MMP-2 production from co-cultures of sarcoma cells with fibroblasts." (PMID 31510956, 2019). "Expression of CD99 and CD73 was suppressed using CD99 or CD73 siRNA in co-cultures of sarcoma cells with fibroblasts." (PMID 31510956, 2019). "Immunohistochemical staining for CIC::DUX4 sarcomas is most notably positive for WT1 and CD99." (PMID 40599504, 2025). "Tumor histology may show a similar appearance to PSS, so to differentiate PSS from other sarcomas, the immunohistochemistry for vimentin, BCL-2, CD99, and TLE1 are common positive markers." (PMID 37170363, 2023). "While 88% of tested Ewing-like sarcomas displayed strong CD99-immunoreactivity, none displayed combined strong BCL11B- and GLG1-immunoreactivity." (PMID 29416716, 2018). "Common immunochemical markers for sarcoma are vimentin, keratin, desmin, leucocyte common antigen, and S100, but not CD99 and MIC2, which characterize primitive neuroectodermal components, a hallmark of immature teratomas." (PMID 27528018, 2016). "Biopsy of renal mass revealed poorly differentiated sarcoma and IHC was positive for vimentin, CD99, and BCL2 and negative for AE1, epithelial membrane antigen, and leukocyte common antigen." (PMID 25610686, 2014). "While CIC-rearranged sarcomas tend to be positive for CD99, WT1, ETV4, and DUX4, these stains are fairly nonspecific and are not sensitive enough to be used alone, thus, there remains a need for specialized genetic testing such as RNA sequencing or RT-PCR for confirmatory diagnosis." (PMID 40599504, 2025). "The morphology was not typical for gastroblastoma and was negative for CD99, ERG, and WT1, which were against CIC/DUX sarcoma." (PMID 36928336, 2023). "While WT1 and CD99 staining are sensitive, they are not specific for CIC-rearranged sarcomas." (PMID 40599504, 2025).
melanoma (24 papers, 2007 to 2025). A malignant, usually aggressive tumor composed of atypical, neoplastic melanocytes. "Conversely, communication patterns of target cells indicated that incoming melanoma cell signaling was predominantly characterized by pattern 1, which including pathways such as CD99 and TNF as well as PARS, TGFb, AGRN, and MPZ." (PMID 39781353, 2025). "Since CD99 signaling can be initiated by other tumor components, in addition to melanoma cells (predicted to generate the strongest signals), we focused our analysis on CRTAM and IFNγ expression in NK‐cells." (PMID 41078003, 2025). "CD99 showed the highest transcription level in malignant glioma and melanoma and lower level in lung cancer, pancreatic cancer, breast cancer and others." (PMID 34611477, 2021). "Compared to the amount of molecules that are known to be involved in leukocyte diapedesis, the knowledge on their role in melanoma diapedesis is limited, although many of these molecules are expressed in melanoma cells such as CD99, CD99L2 and CD54." (PMID 33172202, 2020). "Focusing on the NK‐cell–melanoma interaction, we identified three primary regulatory mechanisms: IFNγ, a cytokine secreted by NK‐cells that plays a crucial role in modulating melanoma cell responses, as well as CD99 and CRTAM, two surface proteins involved in cell adhesion." (PMID 41078003, 2025). "Subsequently, we juxtaposed the potency of signaling molecules across subpopulations, revealing a heightened intensity of CD99 and MK within the C4 PCLAF+ Melanoma cells subtype." (PMID 39781353, 2025). "For example, the predominant signaling in outgoing melanoma cells was typified by pattern 1, encompassing various pathways such as AGRN, VEGF, CD99, and others." (PMID 39781353, 2025). "Other immunohistochemical staining that are helpful in differential diagnosis include: positive CD99 for primitive neuroectodermal tumor, leukocyte common antigen positive for small‐cell lymphomas and S100, Melan‐A and HMB‐45 positive for malignant melanoma." (PMID 36950672, 2023). "Metastatic malignant melanoma, lymphoma and PNET (pancreatic neuroendocrine tumor) were also ruled out based on negative results for S100, LCA (Leukocyte common antigen) and CD99, respectively." (PMID 35797874, 2022). "Unlike CD10 diffuse expression, CD99 positivity was only observed in scattered cells in the recurrent skin tumour, demonstrating the transdifferentiation pathway followed by melanomas in their progression." (PMID 39001214, 2024). "However, staining was negative for CD34, desmin, S-100 protein, cytokeratin, human melanoma black (HMB)-45, B-cell lymphoma (Bcl)-2 and CD99." (PMID 24348865, 2014). "Furthermore, nMCC-UP specimens do not express S-100 and CD45/CD20, which are present in melanoma and lymphoma, respectively, while CD99 could help to distinguish MCC from a primitive neuroectodermal tumor (PNET)." (PMID 36230698, 2022). "The second round immunophenotyping test showed PCK, CD99, OCT3/4, CD117, S100, and HMB45 were all negative while only Syna was positive, which can rule out metastatic carcinoma, germ cell tumor, melanoma, and primitive neuroectodermal tumor." (PMID 38835374, 2024). "Hematolymphoid markers (CD45, B cell, and T cell), myogenic markers (myoglobin, desmin, myogenin), melanoma markers (HMB 45, melan A, tyrosinase) and Ewing’s sarcoma markers (CD99/MIC2) are absent in most ONB cases." (PMID 36452830, 2022). "However, staining for myoglobin, desmin, MSA, SMA, human melanoma, black-45 (HMB-45) and CD99 are often negative, which is consistent with the present case." (PMID 23761028, 2013). "All other markers tested were negative (pan-melanoma, HMB45, Melan A, keratin AE1/AE3, desmin, alpha smooth muscle actin, h-caldesmon, CD34, p16, CD117, DOG1, myogenin, CD10, estrogen receptor (ER), progesterone receptor (PR), PAX8, WT1, synaptophysin, chromogranin A, CD99 and PRAME))." (PMID 39196362, 2024).
rhabdomyosarcoma (22 papers, 2013 to 2025). A rare aggressive malignant mesenchymal neoplasm arising from skeletal muscle. "Some alveolar rhabdomyosarcomas can express CD99, but they also express myogenic markers, including myogenin and MyoD1." (PMID 40950824, 2025). "Rhabdomyosarcomas and desmoplastic small round cell tumour show a cytoplasmic CD99 immunoreactivity while in ES is typic the membranous pattern of immunoreactivity." (PMID 32675940, 2020). "Both Rhabdomyosarcoma and small cell carcinoma lack CD99 positivity." (PMID 40978053, 2025). "However, CD99 can be found in other small blue round cell tumors, including lymphoma, neuroblastoma, and rhabdomyosarcoma." (PMID 39757659, 2025). "CD99 is a sensitive diagnostic marker for EES but is not specific because it is also seen in other tumors such as rhabdomyosarcoma." (PMID 38769118, 2024). "The present case is a unique cervical cancer, consisting of neuroepithelial components positive for CD99 and synaptophysin, immature / atypical intestinal glands positive for SALL4 and CDX-2, cartilage cells, and rhabdomyosarcoma, resembling sinonasal TCS." (PMID 31684979, 2019). "Immunohistochemical analysis showed strong diffuse positivity for CD99, alongside vimentin, BCL2, Cyclin D1, and C-Kit expression, while markers such as CK7, CK20, S100, and CD34 were negative, effectively ruling out differential diagnoses such as rhabdomyosarcoma, lymphoma, and other SRCTs." (PMID 41466962, 2025). "Rhabdomyosarcoma typically shows positive staining for myogenin, desmin, sarcomeric actin, and myoglobin, while it is usually negative for NKX2.2, CD99, CD45, cytokeratin (CK), S100, and neuron-specific enolase (NSE)." (PMID 40094002, 2025).
lymphoma (20 papers, 2013 to 2026). A malignant (clonal) proliferation of B- lymphocytes or T- lymphocytes which involves the lymph nodes, bone marrow and/or extranodal sites. "CD99 influences processes associated with inflammation, immune responses and cancer, including lymphoma/leukemia and myeloid malignancies." (PMID 41557613, 2026). "It should be kept in mind that a subset of lymphomas, including T-cell lymphoblastic lymphomas can express CD99." (PMID 40950824, 2025). "We previously showed that overexpression of CD99 promoted the differentiation of lymphoma cells into terminal B-cells." (PMID 26000982, 2015). "CD99 has been found to be relevant in lymphoma, leukaemia and myeloid malignancies." (PMID 41557613, 2026). "Regarding phenotype, the positivity for CD45 and CD99 with a high Ki-67 proliferation index could suggest a lymphoma, but the morphological similarities between the extramedullary tumour cells and the bone marrow blasts are suggestive for myeloid sarcoma." (PMID 27019694, 2016). "Immunohistochemically, precursor B-cell lymphoblastic lymphoma is positive for CD99, and often nonreactive or only focally positive for conventional lymphoma markers such as LCA, CD20, and CD3." (PMID 25475214, 2014). "Rarely, T-lymphoblastic leukemia/lymphoma with an entirely mature immunophenotype, lacking expression of TdT, CD34, CD1a, and CD99, has been reported in children, and has been associated with poor prognosis, as have cases of T-lymphoblastic leukemia/lymphoma that are TdT negative." (PMID 40227608, 2025). "Additional markers that may be helpful for MRD assessment include CD99, which may be overexpressed in T-lymphoblastic leukemia/lymphoma compared with normal T cells, and CD48, which exhibits reduced expression in T-lymphoblastic leukemia/lymphoma compared with normal T cells." (PMID 40227608, 2025). "LCA positivity supports the diagnosis of lymphoma, but T cell lymphoblastic lymphoma may be negative for LCA and positive for CD99 and CD3." (PMID 23537038, 2013).